STAT6 (signal transducer and activator of transcription 6)
Diseases named in the same sentence as STAT6 in open-access papers (continued):
Sharing a sentence is not in itself a finding about the gene and the disease.
tumor (continued). "We found in 2/3 PMBL cell lines that downregulation of BCL6 / STAT6 sensitizes the tumor cells for treatment with immuno-chemotherapeutic agents." (PMID 25594020, 2014). "IL-4Rα/STAT6 signaling-dependent IL-13 produced by iNKT cells plays an important role in iNKT cell-dependent tumor immunosurveillance." (PMID 23990998, 2013). "For example, treatment with anthracyclines and oxaliplatin results in immunogenic tumor cell death and platinum-based chemotherapeutics downregulate the inhibitory STAT6/PD-L2 pathway and sensitize tumor cells for T cell-mediated cytotoxicity." (PMID 23626745, 2013). "For instance, immunomodulators that have the capacity to induce IL-12 and IFN-γ with novel SMAD3/4 or STAT3 and STAT6 inhibitory molecules are potential targeted mixtures of polarizing the beneficial immune cells within tumor microenvironment." (PMID 21943203, 2011). "Others have demonstrated the contribution of STAT6 to the suppression of an effective anti-tumor immune response in STAT6 -/- mice." (PMID 21595984, 2011). "This is consistent with recent data obtained from tumor cell lines where RA induced the synthesis of Ets-1 and STAT-6, transcription factors that are involved in Th2 differentiation." (PMID 17118196, 2006). "In this study, we tested the hypothesis that ADGRG6 is overexpressed in PAAD and drives tumor progression through NF-κB/STAT6-mediated signaling and modulation of the TME." (PMID 41614755, 2025). "We hypothesized that ADGRG6 is overexpressed in PAAD and predicts unfavorable clinical outcomes by promoting tumor cell proliferation and migration through NF-κB/STAT6-mediated signaling and modulation of the TME." (PMID 41614755, 2025). "In summary, TNFRSF14/HVEM expression in tumor cells promotes Stat5 and Stat6 activation." (PMID 40105652, 2025). "Furthermore, IL-6 or prostaglandin E2, which induces M2-TAM polarization by activating STAT3, STAT1, and STAT6 signaling pathways, can be secreted by tumor cells in response to cisplatin or carboplatin therapy." (PMID 40370720, 2025). "However, persistent STAT3/STAT6 activation also contributes to T-cell exhaustion and dysfunction within the tumor microenvironment, posing a significant challenge for immunotherapy." (PMID 40243506, 2025). "In addition, at the protein level, BBR inhibited tumor-conditioned medium-induced phosphorylation of STAT6, and administration of 30 μm BBR resulted in a 30% decrease in the phosphorylation status of STAT6 compared to the PBS group." (PMID 41585886, 2025). "To validate the results, we independently silenced Stat6 in tumor-conditioned macrophages." (PMID 40588561, 2025). "In addition, M2a macrophages can assist tumor cells in growth through the IL-4/STAT6-mediated pathway, and IL-4 released by tumor cells and M2a macrophages further promotes the polarization of M2 macrophages into M2a, thus forming a positive feedback pathway." (PMID 40703527, 2025). "Similarly, the administration of STAT6 inhibitor AS1517499 significantly attenuated tumor growth and early liver metastasis in an orthotopic 4T1 mammary carcinoma mouse model." (PMID 41409600, 2025). "Additionally, studies have found that drugs can effectively reverse M2-to-M1 polarization via the co-delivery of STAT6 inhibitors, suppressing tumor growth and metastasis." (PMID 40270974, 2025). "Because preoperative differentiation from other neoplasms is challenging, definitive diagnosis relies on histopathological examination and immunohistochemical staining, particularly for STAT6 nuclear expression, a highly specific marker for SFTs resulting from NAB2-STAT6 gene fusion." (PMID 40979027, 2025).
tumor (continued). "In this way, a STAT6 inhibition that dampens the expression of PKM2 could suppress the growth of tumor cells that are highly dependent of glycolysis." (PMID 41409600, 2025). "ERβ activation in macrophages has been shown to inhibit tumor growth in certain cancers by suppressing the JAK1/STAT6 pathway, which may contribute to a less immunosuppressive tumor microenvironment." (PMID 40438106, 2025). "Furthermore, there was moderate and diffuse nuclear expression of the anti-STAT6 antibody in tumor cells, which is consistent with a diagnosis of OMS2020 solitary fibrous tumor." (PMID 40065864, 2025). "Furthermore, western blot analysis of tumor tissues confirmed that myeloid cell-specific Smad4 ablation promoted STAT6 phosphorylation, whereas blocking Fabp2 reversed this phenomenon." (PMID 39664586, 2024). "Next, IHC assay was used to detect the expression of SPIB and STAT6 in tumor tissues." (PMID 39153969, 2024). "Together, these results indicate that STAT6 mutant rrDLBCL cells remodel their tumor microenvironment (TME) via the secretion of the chemokine CCL17 to attract CD4+ T-cells, although the subtype of CD4+ T-cells which were recruited were not determined in this study." (PMID 38285120, 2024). "Conversely, in cancer, the STAT6-lncRNA interplay may influence tumor growth and immune evasion, thereby impacting cancer progression and therapy resistance." (PMID 39353898, 2024). "However, in GBM, IL-13Rα2 competitively binds to IL-13, thereby inhibiting the STAT6 signaling pathway, promoting tumor cell invasion, metastasis, and proliferation, and inhibiting tumor cell apoptosis." (PMID 39506843, 2024). "(f) An intron variant in STAT6 (Signal Transducer And Activator Of Transcription 6), which transduces IL4 and IL13-mediated signaling, regulates the expression of genes involved in the immune response, cell survival, and tumor proliferation and metastasis, hence, it has oncogenic functions in CRC15." (PMID 39715885, 2024). "Thus, it is paramount not only to describe the nuclear staining of STAT6 but also to consider the proportion of tumor cells as well as the intensity of staining." (PMID 38659562, 2024). "However, STAT3 and STAT6 are often over-activated in tumor cells to induce tumor invasion and immune suppression." (PMID 39525474, 2024). "Moreover, STAT6 can influence the tumor microenvironment by modulating immune cell activity, potentially promoting immune evasion and tumor progression." (PMID 39353898, 2024). "Likewise, the differences in the expression levels of STAT2, STAT3, STAT4, STAT5A, STAT5B, and STAT6 between normal and tumor tissues were also displayed." (PMID 36968603, 2023). "Administration of the engineered exosome delivering an antisense oligonucleotide (ASO) targeting STAT6 (exoASO-STAT6), which could selectively silence STAT6 expression in TAMs, induces reprogramming of TAMs and remodeling of the tumor microenvironment." (PMID 37012233, 2023). "To determine whether PTX3 induces desmoid tumor cell proliferation via STAT6 activation, we combined recombinant PTX3 protein treatment with AS1517499." (PMID 37377751, 2023). "In vivo, Pulsatilla saponins could reduce the number of lung metastasis loci, down-regulate the expression of M2 marker genes, and suppress the expression of phosphorylated STAT6 in tumor tissues." (PMID 37175092, 2023). "Targeting STAT6 signaling can inhibit tumor growth and metastasis as well." (PMID 38188683, 2023). "This suggests that PS and AS may inhibit tumor progression through the same target, which further indicates that the tumor-inhibitory effect of PS in vivo may be due to the inhibition action of STAT6 signaling." (PMID 37175092, 2023). "The average expression values of STAT1 (p < 0.001), STAT2 (p < 0.001), STAT3 (p < 0.001), STAT4 (p < 0.001), STAT5A (p < 0.001), STAT5B (p < 0.001), and STAT6 (p < 0.001) among immune subtypes C1-C6 in all tumor types were identified to have notable differences." (PMID 36968603, 2023).
tumor (continued). "The tumor exhibited positive staining for STAT6 and CD34, suggesting SFT." (PMID 37315497, 2023). "IL-4 selectively induces apoptosis in these tumor cells in a Stat6-dependent manner in vitro and in vivo, therefore, treatments that induce upregulation of these cytokines, such as Esperanza extract, could be considered therapeutic alterations." (PMID 37629156, 2023). "For instance, loading exosomes with antisense oligonucleotides targeting STAT6 and using these exosomes in combination with immune therapy has shown great antitumor effectiveness in mice, resulting in over 90% tumor growth inhibition and 50%–80% complete remissions." (PMID 37670933, 2023). "Evidence from other cancer types suggests a role for STAT6 activation in tumor progression." (PMID 37377751, 2023). "In addition, there is evidence that STAT6 can be activated by IL-4 and IL-13 produced by oncogenic Kras driving cells in the tumor microenvironment, and then target cMyc to drive metabolic reprogramming." (PMID 37175092, 2023). "IL‐13 activates the IL‐13 receptor complex to elicit signaling of the JAK1/STAT6 pathway, which may promote cell differentiation and inhibit tumor growth." (PMID 36806727, 2023). "Vacant Tumor microparticle induces macrophage conversion to M2 type via cGAS/STING/TBK1/STAT6 pathway, promoting M2 type macrophage proliferation and M1 type macrophage apoptosis, and M2 type macrophages, in turn, promote TRC proliferation, leading to tumor growth and metastasis." (PMID 35861052, 2023). "We thus hypothesized that PS might exhibit anti-tumor effects by inhibiting M2-like polarization through the STAT6 pathway." (PMID 37175092, 2023). "STAT6 acetylation in TAMs affects their polarization and tumor-killing ability." (PMID 36577755, 2022). "STAT2, STAT4 and STAT6 appear to have more limited roles in tumor biology." (PMID 35163491, 2022). "Another study showed that knockout of lncRNA-MM2P could stop the phosphorylation of STAT6, thus preventing the M2 polarization of macrophages driven by cytokines and weakening the tumor angiogenesis function of M2 macrophages." (PMID 35845962, 2022). "Inhibition of STAT6 with AS led to inhibition of macrophage-induced tumor cell migration." (PMID 35927238, 2022). "However, STAT3 and STAT5 have been studied more thoroughly, while the role of STAT1, STAT2, STAT4, and STAT6 in tumor development has been studied less thoroughly." (PMID 35244291, 2022). "Given that in three FL patients activating STAT6 (i.e. p.D419G, p.D419N, and p.D523V) mutations present in tumor tissue DNA were detectable in plasma cfDNA, it is possible to apply therapies targeting the JAK-STAT6 pathway for the FL patients with these mutations in cfDNA." (PMID 35795062, 2022). "Immunohistochemical staining indicated that the tumor was positive for STAT6, CD34." (PMID 36245559, 2022). "STAT6 activation activates the genes responsible for M2 polarization and tumor growth." (PMID 34861103, 2022). "Inhibitor of STAT6 (AS1517499) combined with 5-fluorouracil markedly reduce the tumor load." (PMID 35600336, 2022). "Higher oxidative stress induced by fatty acid oxidation increases de-phosphorylation of STAT6-specific tyrosine phosphatase (SHP1) and Phos-tyr641-STAT6, which correlate with and presumably support the immunosuppressive and tumor-promoting functions of macrophages." (PMID 36038892, 2022). "In the surgical specimen, tumor cells were positive for STAT6 and CD34." (PMID 36550858, 2022). "We examined whether STAT6 inhibitor AS1517499 and anti‐Chi3L1 antibody combination treatment showed additive effects on tumor migration by STAT6‐dependent M2 polarization." (PMID 34861103, 2022). "On IHC, all SFTs showed a variable degree of STAT6 positivity in the tumor nuclei." (PMID 35105348, 2022). "Interestingly, we observed similar IL-10 mRNA transcripts in the colon of both the WT and STAT6−/− AOM/DSS-treated mice during the advanced stages of tumor development." (PMID 33919941, 2021).
tumor (continued). "In this context, >90% of SFT express CD34 and STAT6, while a smaller percentage of tumours may be positive for CD99 (70%), EMA (20%), smooth muscle actin (20%) and BCL-2 (30%)." (PMID 34849218, 2021). "Because the balance between Th17/Treg cells and these regulatory factors is decisive in CAC progression, it could be interesting to determine if the tumor growth observed in STAT6−/− mice after Treg depletion is Th17-mediated." (PMID 33919941, 2021). "In addition, a number of studies have demonstrated that M2 macrophages had tumor-promoting properties and Stat6 was the major transcription factor responsible for the induction of M2 genes." (PMID 34880862, 2021). "STAT6 is also constitutively activated and involved in tumor initiation and progression." (PMID 34741044, 2021). "In contrast, we found an increased Treg frequency in the blood and spleen of STAT6−/− AOM/DSS animals at Day 20 (early stages of tumor development), compared to the control and WT AOM/DSS mice (17.5 ± 1 vs. 9.44 ± 0.1, p < 0.05; 17.5 ± 1 vs. 9.8 ± 3.3, p < 0.05)." (PMID 33919941, 2021). "Over-expression of IL-12 could inhibit IL-4 and STAT6 in human CC stem cells and inhibit the survival of CC stem cells in vitro and their tumor formation ability in mice." (PMID 33450900, 2021). "Indeed, direct analysis of TAMs isolated from B16-OVA tumor-bearing Maoa WT and Maoa KO mice confirmed that compared to wild-type TAMs, MAO-A-deficient TAMs showed reduced Stat6 activation (i.e., reduced Stat6 phosphorylation)." (PMID 34112755, 2021). "Hepatoma carcinoma cell-derived exosomal miR210 might enter endothelial cells, and affect SMAD4 and STAT6 to promote tumor angiogenesis." (PMID 34098850, 2021). "Interestingly, we found that tumor growth was restored in STAT6−/− mice with the Treg cells reduction, and extensive chronic inflammation was reestablished." (PMID 33919941, 2021). "Current data describe STAT6 as an essential factor in metastasis in PCa, but its exact role in tumor progression is still largely unknown, and further investigation is needed." (PMID 34638338, 2021). "Hence, we posit that LINC01119 induces SOCS5 expression, which then inhibits STAT6, relieving its tumor-suppressive functions in TNBC cells." (PMID 34059683, 2021). "However, there are very few studies in this regard, and more research must be generated to determine if the activation of the STAT6 homodimer or the STAT6/STAT2 heterodimers can contribute to the process of tumor recognition and elimination." (PMID 33076315, 2020). "Additionally, STAT6 is an important target protein of IL-4 that likely regulates the microenvironment of tumor cell growth, inhibits tumor invasion, and reduces tumor proliferation and differentiation." (PMID 33013320, 2020). "Moreover, they observed in their tumor models that the activation of STAT6 correlates with smaller tumor sizes and better survival." (PMID 33076315, 2020). "For example, diminished STAT6 phosphorylation results in downregulation of the T cell inhibitory molecule programmed death ligand 2 (PD-L2) on both DCs and tumor cells, which enhances tumor cell recognition by T cells." (PMID 31980913, 2020). "Another study evaluated the effect of gene silence of STAT6 on tumor growth." (PMID 33287240, 2020). "We next compared the effects of STAT6−/− CD11b+ and STAT6+/+ CD11b+ cells on tumor growth in vivo." (PMID 31798581, 2019). "The downregulation of Stat1, Stat4 and Stat6 observed in tumour tissue may confirm the reduced response to cytokines of lymphocytes and therefore may indicate a decrease in lymphocyte activation." (PMID 31595196, 2019). "The heightened tumor immunity in STAT6-deficient mice is likely not due to the balance between CD4+, Th1, and Th2 cells, which is consistent with the results from other studies." (PMID 31798581, 2019).
tumor (continued). "Accordingly, the myeloid cell's Trim24 deficiency impaired the tumor infiltration of IFNγ-producing CD4+ and CD8+ effector T cells, suggesting that Trim24 deficiency impaired antitumor immunity through suppressed Stat6 acetylation in TAMs." (PMID 31554795, 2019). "We found that IL-4 is significantly reduced in the BALF of STAT6−/− tumor-bearing mice." (PMID 31798581, 2019). "Moreover, published studies have suggested that genetic deletion or pharmacological inhibition of Stat6 dramatically suppresses tumor growth and promotes the antitumor immune responses of macrophages." (PMID 31554795, 2019). "Additionally, the levels of phospho-STAT6 showed a rising level, which was evidenced on the 21st day of tumour development (W group)." (PMID 30975087, 2019). "STAT6 deficiency in CD11b+ cells but not tumor cells decreased interleukin (IL)-4 secretion and the differentiation of CD11b+ cells into M2 macrophage cells." (PMID 31798581, 2019). "Activation of the STAT6 signaling pathway is also important for macrophage function and required for alternative (M1 and M2) activation of macrophages, which affects inflammation and tumor growth." (PMID 31798581, 2019). "Small interfering RNA was used to downregulate the expression of STAT6 in tumor cells." (PMID 31798581, 2019). "Previous studies indicate that STAT6 plays a role in macrophage polarization, and a change in this potential could affect carcinogenesis and neoplasm progression." (PMID 31798581, 2019). "We found that reduced IL-4 secretion is mainly attributed to STAT6 deficiency in CD11b+ cells but not tumor cells." (PMID 31798581, 2019). "In addition, further studies demonstrated that lncRNA-MM2P promoted M2 polarization of macrophages by reducing phosphorylation on STAT6, then affecting macrophage-mediated tumorigenesis and tumor growth." (PMID 31448238, 2019). "For example, the role of p-STAT5/p-STAT6 in tumor cell migration and invasion is still unknown, and further investigations on their function are necessary." (PMID 31718693, 2019). "In addition to the detection of the NAB2-STAT6 fusion gene, immunohistochemical nuclear staining of STAT6 by the translocated NAB2-STAT6 fusion protein to the nucleus is a gold marker for this tumor." (PMID 29168109, 2018). "Immunohistochemically, the tumor cells expressed STAT6 and CD34." (PMID 30168002, 2018). "Tumour grade along with immunohistochemistry for Ki67, STAT6, PHH3, CD34 and Bcl-2 were assessed." (PMID 30183767, 2018). "Genetic deletion of Stat3 and Stat6 impaired tumour development and invasion in vivo." (PMID 29065107, 2017). "This strongly supports the hypothesis that IL-4/STAT6 signaling may be beneficial to tumor growth possibly by several mechanisms, including gaining resistance to apoptosis and escaping the immune surveillance." (PMID 28927416, 2017). "Compared with PBMCs, p65 and STAT6 were both enhanced in the TAMs of clinical tumor samples." (PMID 26540574, 2016). "The necrotic foci were also devoid of CD68+ cells having the morphological features of myeloid cells with scavenger activity, whereas some of the CD68 positivity in the areas surrounding the necrosis was due to the presence of tumour cells, as demonstrated by their STAT6-positive nuclei." (PMID 27304187, 2016). "Finally, IR-induced IL-4 promotes tumor progression and metastasis by increasing β-catenin/Stat6 through activation of JAK/JNK in human cancer cells." (PMID 27895317, 2016). "We evaluated whether the classical signaling pathways of IFN-γ (STAT1) and IL-13 (STAT6) were activated in tumor cells following culture in activated lymphocyte-conditioned medium." (PMID 24911872, 2014). "Conversely, ectopically activated Stat6 is frequently found in tumor samples." (PMID 24314139, 2013). "In addition, human and murine studies in pancreatic cancer have shown high local production of TSLP (another STAT6-activating cytokine), resulting in Th2 skewing and enhanced tumor outgrowth." (PMID 22611421, 2012).